TNFSF13B (TNF superfamily member 13b)
Description:
Cytokine that binds to TNFRSF13B/TACI and TNFRSF17/BCMA. TNFSF13/APRIL binds to the same 2 receptors. Together, they form a 2 ligands -2 receptors pathway involved in the stimulation of B- and T-cell function and the regulation of humoral immunity. A third B-cell specific BAFF-receptor (BAFFR/BR3) promotes the survival of mature B-cells and the B-cell response. Isoform 2 seems to inhibit isoform 1 secretion and bioactivity. [Isoform 3]: Acts as a transcription factor for its own parent gene, in association with NF-kappa-B p50 subunit, at least in autoimmune and proliferative B-cell diseases. The presence of Delta4BAFF is essential for soluble BAFF release by IFNG/IFN-gamma-stimulated monocytes and for B-cell survival. It can directly or indirectly regulate the differential expression of a large number of genes involved in the innate immune response and the regulation of apoptosis.
Synonyms: BLyS; TALL-1; CD257; BAFF; TALL1; TNFSF20; ZTNF4; THANK; TNLG7A
Tractability: Small molecule: a structure with a bound ligand is known; it has a binding pocket of medium quality. Antibody: an approved drug acts on it; its Gene Ontology location is reachable by antibodies, with high confidence; UniProt places it where antibodies can reach, with medium confidence; UniProt predicts a signal peptide or a membrane-spanning region; the Human Protein Atlas places it where antibodies can reach. Other modalities: a drug acting on it is in phase 2 or 3 trials.
Target class: Secreted protein
Gene: Protein-coding gene on chromosome 13 (108,251,240 to 108,308,484, forward strand). Ensembl gene ENSG00000102524.
Subcellular location: Cell membrane; Secreted (Tumor necrosis factor ligand superfamily member 13b, soluble form)
Subcellular location (Human Protein Atlas): Plasma membrane; Focal adhesion sites; Vesicles; Predicted to be secreted
Pathways (Reactome):
Immune System: TNF receptor superfamily (TNFSF) members mediating non-canonical NF-kB pathway; TNFR2 non-canonical NF-kB pathway; TNFs bind their physiological receptors
Gene Ontology:
Molecular function: protein binding; cytokine activity; signaling receptor binding; tumor necrosis factor receptor binding
Biological process: positive regulation of B cell proliferation; immune response; lymphocyte homeostasis; signal transduction; B cell activation; B cell differentiation; cell communication; gene expression; signaling; skin development; tumor necrosis factor-mediated signaling pathway
Cellular component: cytoplasm; perinuclear region of cytoplasm; plasma membrane; extracellular region; membrane
Genetic constraint (gnomAD): Loss-of-function variants: 6 observed, 26.18 expected, observed/expected ratio (o/e) 0.23, 90% interval 0.12 to 0.45. The upper end of that interval is the gene's LOEUF score, 0.45, which puts it in group 2 of 6, group 1 being the genes least tolerant of losing a copy. Missense variants: 228 observed, 322.14 expected, observed/expected ratio (o/e) 0.71, 90% interval 0.63 to 0.79. Synonymous variants: 116 observed, 126.41 expected, observed/expected ratio (o/e) 0.92, 90% interval 0.79 to 1.07.
Homologues: Orthologues: chimpanzee TNFSF13B (99% identical), macaque TNFSF13B (96% identical), rabbit TNFSF13B (84% identical), dog TNFSF13B (80% identical), guinea pig TNFSF13B (72% identical), pig TNFSF13B (70% identical), rat Tnfsf13b (67% identical), mouse Tnfsf13b (67% identical), tropical clawed frog tnfsf13b (40% identical), zebrafish tnfsf13b (35% identical). Paralogues in human: TNFSF13 (20% identical), TNFSF12 (13% identical).
Diseases named in the same sentence as TNFSF13B in open-access papers:
TNFSF13B is named in the same sentence as 417 diseases in open-access papers, as found by Europe PMC text mining. Sharing a sentence is not in itself a finding about the gene and the disease. The quoted sentences say what the papers report.
systemic lupus erythematosus (352 papers, 2006 to 2025). An autoimmune multi-organ disease typically associated with vasculopathy and autoantibody production. "A genetic variant in TNFSF13B, encoding BAFF, causing its abnormal expression and leading to an excess of B-cell activation, has been associated with MS as well as with systemic lupus erythematosus." (PMID 39960641, 2025). "In addition, genomics research retrospectively linked a variant on TNFSF13B with an augmented risk of MS and systemic lupus erythematosus (LES) and a blood increase in soluble BAFF, which is already a target of belimumab, a monoclonal antibody approved for LES and in clinical trials for MS." (PMID 36793897, 2023). "We found increased expression of Tnfsf13b, encoding the B/plasma cell survival factor BAFF, in lupus-enriched TrMac subsets (MNP1.3, 1.4, and 1.5) in MRL-Lpr kidneys compared with MRL-MpJ, with little Tnfsf13b expression in MoMac subsets." (PMID 36345939, 2022). "As an example, in a GWAS analysis it was uncovered the association of multiple sclerosis and systemic lupus erythematosus with a genetic variant in the 3’UTR of the TNFSF13B gene, which encodes the cytokine B-cell-activating-factor (BAFF)." (PMID 34531863, 2021). "The impairment of TNFSF13B has been described in autoimmune diseases such as systemic lupus erythematosus, Sjögren syndrome, and especially, rheumatic diseases, although always with significantly higher levels than the healthy controls." (PMID 31772502, 2019). "The B cell survival factor (TNFSF13B/BAFF) is often elevated in autoimmune diseases and is targeted in the clinic for the treatment of systemic lupus erythematosus." (PMID 29572442, 2018). "A rare variant (BAFF-var) of the tumor necrosis factor superfamily 13b (TNFSF13B) gene has been recently associated with multiple sclerosis (MS) and systemic lupus erythematosus (SLE)." (PMID 29844438, 2018). "Overexpression of TNFSF13B can lead to autoimmune consequences, such as system lupus erythematosus (SLE) or Sjögren’s syndrome." (PMID 28822103, 2018). "Its knockdown in vitro results in decreased expression of select female-biased immune transcripts, including B cell–activating factor (BAFF; also known as B lymphocyte stimulator and TNFSF13B), the target of belimumab, the only biologic currently used to treat systemic lupus erythematosus." (PMID 33183347, 2020). "In this regard, a genetic variant of the TNFSF13B (TNF superfamily member 13b) gene has been recently involved in the susceptibility to several autoimmune disorders, including multiple sclerosis (MS), rheumatoid arthritis (RA), and systemic lupus erythematosus (SLE)." (PMID 30586461, 2018). "TLR activation by S100A9, alongside TLR–TNFSF13B interaction, cooperatively enhanced survival signals delivered to myeloma cells, consistent with the previous finding that TLR+ plasma cells showed higher level of autoantibodies against dsDNA in TNFSF13B-dependent lupus." (PMID 34150664, 2021).
autoimmune disease (253 papers, 2006 to 2025). A disorder resulting from loss of function or tissue destruction of an organ or multiple organs, arising from humoral or cellular immune responses of the individual to their own tissue constituents. "TNFSF13B variants have been associated with RA in several studies and also with other autoimmune diseases such as systemic erythematous lupus." (PMID 38954480, 2024). "We have previously shown that a variant of the TNFSF13B gene that we called BAFF-var increases the production of the cytokine BAFF, upregulating humoral immunity and increasing the risk for certain autoimmune diseases." (PMID 33123155, 2020). "Increased serum levels of TNFSF13B protein have previously been found in autoimmune diseases, and CXCL11 has also been implicated in autoimmune diseases." (PMID 25298177, 2014). "The insertion–deletion variant in the 3′UTR of the TNFSF13B gene (encoding BAFF) associated with increased risk of autoimmune diseases creates an APA site that generates a shorter transcript (BAFF-var mRNA) that is more efficiently translated and hence produces higher levels of sBAFF." (PMID 33123155, 2020). "In this regard, performing further studies to elucidate the specific association of TNFSF13B BAFF-var with other autoimmune diseases would be of great interest as new therapy approaches involving BAFF could emerge." (PMID 29844438, 2018). "Once the expression of TNFSF13B is dysregulated, it disrupts B cell self-tolerance, leading to autoimmune diseases and B cell malignancies." (PMID 37587523, 2023). "Data from clinical trials has proved that blocking TNFSF13B via blocking reagents is an effective approach for some autoimmune diseases." (PMID 32384708, 2020). "The association of TNFSF13B BAFF-var with RA and SLE observed in our study extends the number of overlapping genetic risk factors across different autoimmune diseases." (PMID 29844438, 2018). "Moreover, TNFSF13B plasma levels increased in all cases over the treatment course, which parallels observations after Rituximab treatment of other autoimmune diseases." (PMID 39304742, 2025). "Earlier studies showed that blocking TNFSF13B/TNFRSF13C signaling may effectively treat autoimmune diseases mediated by B-cells in humans." (PMID 35432452, 2022). "Polyclonal B-cell activation might be related to pathogenic over-expression of B-cell-activating factor (BAFF; also known as TNFSF13B, BLyS, THANK and TALL-1) in primary Sjögren's syndrome (pSS) and other autoimmune diseases." (PMID 16507129, 2006).
Autoimmunity (134 papers, 2006 to 2026). The occurrence of an immune reaction against the organism's own cells or tissues. "In this regard, a TNFSF13B insertion-deletion variant, which leads to higher levels of BAFF, has been proposed as a common genetic risk factor in autoimmunity." (PMID 30586461, 2018). "Our findings support the important role of rare variants, such as TNFSF13B BAFF-var, in understanding the unknown mechanisms of autoimmunity." (PMID 29844438, 2018). "BAFF (TNFSF13B) overexpression is well established as a driver of autoimmunity, targeted by belimumab." (PMID 31921420, 2019). "Interestingly, not far from MYO16, in the chr13:108090996-108968251 region highlighted by HH analysis, is located the TNFSF13B gene, encoding the cytokine and drug target B-cell activation factor (BAFF) whose overexpression is related to autoimmunity." (PMID 34889895, 2021). "TNFSF13B (BAFF) secretion has been demonstrated from EC in the bone marrow, as well as in the settings of malignancy, autoimmunity and viral infection." (PMID 33936069, 2021).
rheumatoid arthritis (113 papers, 2006 to 2025). A chronic, systemic autoimmune disorder characterized by inflammation in the synovial membranes and articular surfaces. "Genes showing lower levels of expression in AD included ICAM-1, IL-1B, CCR1, IFIH1, SOCS1, TNFAIP3 and TNFSF13B, which are strongly associated with acute and chronic inflammation and adult rheumatoid arthritis." (PMID 26310571, 2015). "The aim of this study was to investigate the association between TNFSF13B BAFF-var and susceptibility to rheumatoid arthritis (RA) and replicate that association in SLE." (PMID 29844438, 2018). "An undergoing study, PREDICT, was launched to explore a variant of the TNFSF13B gene, commonly known as BAFF-var, that is linked to an elevated risk of developing immune-mediated diseases, including SLE and rheumatoid arthritis (RA)." (PMID 39339212, 2024). "Overexpression of the cytokine and drug target B-cell activating factor (BAFF; encoded by TNFSF13B) has been associated with susceptibility to SLE, multiple sclerosis and rheumatoid arthritis." (PMID 32151092, 2020). "Use of a soluble form of TACI that antagonizes both APRIL and the closely related B-cell activation factor from the TNF family (BAFF, TNFSF13B) ameliorated rheumatoid arthritis (RA) in mouse models." (PMID 19788740, 2009).
myeloma (72 papers, 2009 to 2025). "Notably, TNFSF13B has been proven to be associated with myeloma cell proliferation and myelomagenesis." (PMID 34150664, 2021). "Nevertheless, the correlations of TNFRSF13B with myeloma-related genes and shorter survival, alongside TNFRSF13B mutations that thwarted MM advancement, indicate the importance of TNFSF13B signal in the MM prognosis of patients." (PMID 34150664, 2021). "TNFSF13B markedly boosted myeloma cell proliferation, and this effect was suppressed after adding Bortezomib, a proteasome inhibitor." (PMID 34150664, 2021). "The correlation analyses for expressions of TNFSF13B and its receptors well-characterized their distinct functions and indicated a potential link between myeloma cells and macrophages." (PMID 34150664, 2021). "Taken together, the surface expressions of TNFSF13B receptors were upregulated on human myeloma cells, promoting myeloma cell proliferation and survival via TNFSF13B signal transduction through the canonical NF-κB pathway." (PMID 34150664, 2021). "Consistent with other observations, our previous study has recognized neutrophils as the major source of TNFSF13B in the spleen, which keep myeloma cells from apoptosis." (PMID 34150664, 2021). "In-vitro analysis of patient primary myeloma cells further demonstrated that enhanced TNFSF13B signaling triggered the canonical NF-κB pathway to boost tumor cell proliferation." (PMID 34150664, 2021). "We subsequently assessed the efficacy of coculture of TNFSF13B with patient myeloma cells and significant pathways involved in the process." (PMID 34150664, 2021). "Based on correlation analysis of integrated scRNA-seq and bulk RNA-seq datasets from patients, we confirmed that myeloid-derived S100A9 was involved in TNFSF13B-dependent myeloma cell proliferation and survival." (PMID 34150664, 2021). "In the animal experiments, we proved that S100A9 was required for both TNFSF13B production by myeloid cells and myeloma cell survival." (PMID 34150664, 2021). "TNFSF13B is abundant in several cell types with close contact to B cells and myeloma cells, which indicates multiple sources of TNFSF13B signaling from neighboring cells." (PMID 34150664, 2021). "TNFSF13b promotes the shifting of human monocytes into osteoclastic cells, whereas blocking TNFSF13b reverses multiple myeloma-mediated osteoclast formation." (PMID 31627291, 2019). "Serine/threonine kinase Pim together with NFκB pathways is shown to regulate TNFSF13b-mediated survival of multiple myeloma cells and osteoclasts." (PMID 31627291, 2019). "We found the correlation of myeloid-derived S100A9 with TNFSF13B dependency in myeloma cells." (PMID 34150664, 2021). "Specifically, TNFSF13B expression had close interactions with macrophage marker genes, namely, TLR and S100A9 genes; their receptor genes, TNFRSF13B and TNFRSF17, showed significant associations with the myeloma-related genes CD38, SDC1, and MYEOV." (PMID 34150664, 2021). "Our results demonstrated that S100A9 administration upregulated TNFRSF13B and TNFRSF17 surface expressions on myeloma cells, indicating crosstalk between TLR activation and TNFSF13B signaling." (PMID 34150664, 2021). "This protection may be attributed to enhanced TNFSF13B signal transduction via S100A9/TLR binding, which has been proven to be critical for myeloma growth." (PMID 34150664, 2021). "In conclusion, myeloid-derived S100A9 can enhance TNFSF13B/TNFRSF13B expression on myeloma cells, stimulating both canonical and non-canonical NF-κB pathways and thereby fuels tumor cell proliferation." (PMID 34150664, 2021). "To confirm whether the difference in NF-κB signaling was present in MM, we determined p38 and p65 phosphorylation levels in myeloma cells treated with TNFSF13B, with or without Bortezomib, for 30 min." (PMID 34150664, 2021).
Sjögren’s syndrome (72 papers, 2006 to 2026). "For example, TNFSF13B induces symptoms resembling those of human Sjogren’s syndrome and SLE when overexpressed in mice." (PMID 34367180, 2021). "Current researches indicated that TNFSF13B, which might be significantly affected by IFN regulatory factors, is an important regulatory target in primary Sjögren's syndrome (SS)." (PMID 32311223, 2020).
lupus nephritis (64 papers, 2008 to 2026). Glomerulonephritis in the context of systemic lupus erythematosus. "Interestingly, as observed in murine MRL-Lpr MNP1 clusters, TNFSF13B (encoding BAFF) expression was increased in TrMacs in human lupus nephritis compared with control kidneys, and macrophage BAFF expression was validated in biopsies obtained from patients with lupus nephritis." (PMID 36345939, 2022). "TrMacs in mouse and human lupus nephritis also showed increased expression of TNFSF13B, encoding BAFF, a cytokine that enhances B cell survival and proliferation and contributes to the plasma cell niche." (PMID 36345939, 2022). "In lupus nephritis (LN), proximity extension assay proteomics identified urinary ICAM-2, FABP4, FASLG, IGFBP-2, SELE, and TNFSF13B/BAFF as markers distinguishing active LN from inactive SLE, correlating with histologic activity indices." (PMID 41262438, 2025).
lymphoma (52 papers, 2006 to 2026). A malignant (clonal) proliferation of B- lymphocytes or T- lymphocytes which involves the lymph nodes, bone marrow and/or extranodal sites. "Besides, studies revealed that genetic variants of both TNFSF13B and TNFSF13B‐receptor were related to SS‐related lymphoma." (PMID 32311223, 2020).
multiple sclerosis (46 papers, 2006 to 2025). A progressive autoimmune disorder affecting the central nervous system resulting in demyelination. "TNFSF13B variants are associated with multiple sclerosis and SLE, and TNFSF13B is a key factor in the survival of B lymphocytes." (PMID 32655996, 2020). "For example, a small deletion (rs374039502) causes the appearance of a new PAS motif within the TNFSF13B gene and has been associated with a higher risk of both multiple sclerosis and SLE in the Sardinian population." (PMID 31475030, 2019). "A variant in the TNFSF13B gene, which encodes for BAFF, has been associated with increased serum levels of this cytokine and has been linked to multiple sclerosis and SLE." (PMID 37795085, 2023). "In particular, people with multiple sclerosis on natalizumab had lower CD6, CDCP1, CXCL13, CXCL9, NfL, TNFRSF10a, TNFSF13B and VCAN (P < 0.036)." (PMID 37361716, 2023).
atherosclerosis (32 papers, 2013 to 2025). A disease characterized by the build-up of fatty material and calcium deposition in the arterial wall resulting in partial or complete occlusion of the arterial lumen. "In the atherosclerosis dataset GSE28829, CD14 (AUC = 0.938), C1QB (AUC = 0.947), CD53 (AUC = 0.952), LY96 (AUC = 0.904), P2RX7 (AUC = 0.981), C3 (AUC = 0.817), and TNFSF13B (AUC = 0.875) demonstrated favorable diagnostic efficiency for differentiating patients with atherosclerosis from controls." (PMID 37649719, 2023). "Taken together, the TNFSF13B seems to have diverse effect on the development of atherosclerosis via different receptors." (PMID 37649719, 2023). "Overall, further research is required to gain a comprehensive understanding of the complex role of TNFSF13B in the pathogenesis of atherosclerosis and PD." (PMID 37649719, 2023). "A study has shown that the TNFSF13B antibody improved atherosclerosis lesions in mice with low plasma cholesterol levels but worsened the lesions in mice with high cholesterol levels, further indicating the diverse effect of TNFSF13B." (PMID 37649719, 2023). "The role of TNFSF13B in the development of atherosclerosis is still under debate." (PMID 37649719, 2023). "Overexpression of TNFSF13B can activate the BAFF-binding receptor TACI, promoting the production of anti-oxLDL IgM and reducing atherosclerosis." (PMID 37649719, 2023). "The co-expression of BAFF/TNFSF13B and APRIL/TNFSF13 in the plaque lymphocytes and macrophages up-regulate FURIN, the primary Proprotein convertase subtilisin/Kexin (PCSK), which inactivates lipases and regulates inflammation in atherosclerosis." (PMID 33262760, 2020).
viral infection (29 papers, 2011 to 2025). "Limited prior work showed that endothelial cells may produce TNFSF13B (BAFF/BLyS), mostly in the context of viral infection or malignancy." (PMID 33936069, 2021).